IL6 (interleukin 6)
Diseases named in the same sentence as IL6 in open-access papers (continued):
Sharing a sentence is not in itself a finding about the gene and the disease.
co-infection (continued). "In this study, co-infection of T. gondii and C. jejuni further increased the levels of IFN-γ and IL-6 caused by T. gondii, much in the same way as the changes in cytokines induced by C. jejuni in gnotobiotic mice, which suggests that T. gondii infection promotes C. jejuni infection symptoms." (PMID 30186279, 2018). "Only IFN-ω, TNF-α, IL-6 and IP-10 were in fact differentially modulated during co-infections." (PMID 28644900, 2017). "suis co-infection potentiates the up-regulation of IL-6, CCL5 and TNF-α." (PMID 27213692, 2016). "Co-infection increases significantly and may be associated with elevated C-reactive protein (CRP), procalcitonin (PCT), and Interleukin-6 (IL-6)." (PMID 26744628, 2016). "IL-6 levels positively correlated with decreased lung function (p<0.001), S. aureus density in sputa (p = 0.0016), SCVs (p = 0.0209), exacerbations (p = 0.0041) and co-infections with S. maltophilia (p = 0.0195) or A. fumigatus (p = 0.0496)." (PMID 27861524, 2016). "To examine the immune profile of individuals with co-infection, we compared the concentration of 15 immune markers (IL-1β, IL-6, IL-8, TNF-α, IL-7, G-CSF, MCP-1/CCL2, MIP-1-α/CCL3, IL-12, IFN-γ, IL-13, IL-17A, GM-CSF, IL-10, and TGF-β1) among the three groups using Kruskal-Wallis ANOVA." (PMID 27128316, 2016). "IL-8, CCL2, and IL-6 were also remarkably increased in the co-infection group." (PMID 25906258, 2015). "This study, to the best of our knowledge, represents the first report reflecting the delicate link between NF-κB, TNF-α, IL-6, FoxP3 splice variants and HO-1 genes and their relationship with HIV disease progression and explains how Mtb co-infection modulates these links to the advantage of HIV." (PMID 25198707, 2014). "Thus, combined IL-6 and IL-10 measurement might be clinically valuable for early identification of SMPP cases at risk of co-infection, facilitating timely intervention and improved patient outcomes." (PMID 40487016, 2025). "In general, the observed impaired production of Th1 cytokines (IFN-gamma and IL-2) and pro-inflammatory cytokines (TNF-alpha and IL-6) during HIV co-infection in LTB-infected individuals might favor intracellular Mtb growth and fail to control the conversion of LTBI into ATB." (PMID 39514524, 2024). "In piglets treated with the orally administered engineered strain, the levels of IL-1β, IL-6, and IL-10 in the co-infection group were lower than those in the challenge group, indicating that the inflammatory response caused by PEDV was milder in the co-infection group." (PMID 38430229, 2024). "Thus, IL-1α, IFN-α and IL-6 mRNA expression were measured at 3 hpi and at 24 hpi in co-infection." (PMID 39772252, 2024). "In addition, ELISA analysis revealed that the worse outcomes of co-infection conditions would be due to the facts that E. hellem infection alone down-regulated the expressions of pro-inflammatory cytokines IL-6 and IL-12, and detained the surge of cytokine levels in the co-infection conditions." (PMID 38199846, 2024). "In order to elucidate the divergent effects of PA/HRV co-infection on IL-6 mRNA and protein levels in bronchial epithelial cells, we tested if cell-free conditioned basal media of co-infected cells contain soluble factors that are able to degrade recombinant IL-6 (rIL-6)." (PMID 35265536, 2022). "KSHV encodes a viral interleukin 6 (vIL-6) that mimics many functions of human IL-6 (hIL-6), since they can both stimulate the proliferation of tumors caused by KSHV and play a role in the inflammatory cytokine syndrome associated with HIV and KSHV co-infection." (PMID 25421888, 2014). "For instance, in co-infection models involving bacteria and IAV, enhanced activity of MAPKs such as p38 and ERK1/2 leads to excessive IL-6 production." (PMID 40692679, 2025). "There was an elevated trend in IFN-λ1, IL-6, ISG15, and MCP-1 expression with H3N2 (4550) infection, which were suppressed upon co-infection with SCoV2/BA." (PMID 40431161, 2025).
co-infection (continued). "At baseline, sTNFR1 and sTNFR2 concentrations were higher in participants with HIV/HCV co-infection than those with HCV mono-infection, whereas IL-6 and sCD163 concentrations were similar in the two groups." (PMID 41394829, 2025). "Logistic regression was used to understand and model the relationship between IL-6 levels (log-transformed) and the variables age, sex, HIV co-infection and death." (PMID 39670465, 2025). "In contrast, the expression levels of IL-6, IL-8, and TNF-α were decreased in cells coinfected with vL126A/ΔNLS and S. suis compared to wild-type PRRSV-2 and S. suis co-infection." (PMID 38547254, 2024). "The results showed that the levels of IL-6, IL-10, IFN-α, and IFN-γ (from 12 hpi to 96 hpi) in the co-infection cells were significantly higher compared to the ALV-J and CIAV mono-infected cells or the controls." (PMID 38674684, 2024). "The optimal cut-off values to predict bacterial co-infection according to Youden’s J statistics in the studied cohort are CRP = 220 mg/L (SE = 0.524; SP = 0.806), PCT = 0.8 μg/L (SE = 0.667; SP = 0.944), and IL-6 = 40 ng/L (SE = 0.714; SP = 0.750)." (PMID 38391578, 2024). "The previous studies related to the expression level of IL-6 during HIV and LTB co-infection are very limited." (PMID 39514524, 2024). "Distinctly, VL1 patient, that has disorganized spleen and VL-HIV coinfection was related to SOD1, STAT3, STAT4, ICOS, TRAF6 and IRF3 genes, and CD8+ cells in the RP and expression of IL6 in both regions of spleen." (PMID 38843306, 2024). "Co-infection of monocytes with PRRSV-2 strain IAF-Klop and S. suis led to synergistic effects on the expressions of IL-6, CCL5, and TNF-α, and additive effects on productions of CCL4, CCL14, CCL20, IL-15, and PTGS2 (COX-2)." (PMID 38547254, 2024). "Meanwhile, many inflammatory factors were increased in EBV coinfection groups: CRP was highest in EBV/fungi coinfection, while PCT and IL-6 were increased significantly in EBV/bacteria coinfection, indicating more complicated syndromes in EBV coinfections." (PMID 37026057, 2023). "Authors presented data on the correlation of IL-6 hypersecretion in HIV patients with TB-infection, and of hypersecretion of IL-6 and IL-8 with an aggravated course of HIV/TB co-infection characterized by a severe lung damage." (PMID 35804391, 2022). "Overall, the results showed upregulation of cytokines IL-10, IFN-γ, and IL-6 and downregulation of IL-12p70, Il-2, and TNF-α during severe Babesia co-infection in mice." (PMID 35719355, 2022). "IL-6 median levels were higher among those with single P. falciparum (124.5 [36.9–433.9] pg/mL) and a P. falciparum/STH co-infection (25.5 [4.4–60.8] pg/mL)." (PMID 35421083, 2022). "IL-6 and IL-1 blockade were helpful in patients with ARDS, patients with co-infection undergo appropriated microbial culture for antibiotic treatment." (PMID 34649460, 2021). "Compared with the group infected with GTPV alone, the expressions of IL-1β, IL-6, IL-10, and IFN-α in the co-infection groups were inhibited." (PMID 33827620, 2021). "We have previously shown that proinflammatory mediators (NOS2, IL-6, and TNF-α) increase in the heart of mice after co-infection with T. cruzi strains, and that fenofibrate is able to modulate this response." (PMID 33072115, 2020). "The levels of TNF-α, IL-1β, IL-6, IL-10, IL-12, mKC, and IFN-γ were significantly increased at 4 h or/and 24 h after MRSA co-infection." (PMID 31849655, 2019). "Of note, while in co-infections the detrimental effects of IFN-γ have been described, this is less clear for IL-6 but suggested by the positive effect of IL-6 neutralization on systemic dissemination." (PMID 31474978, 2019). "In summary, HBV-infected patients had a unique biomarker clustering profile comprising IFN-γ, IL12p70, IL-10, IL-6, and TNF-α that was distinct from the profile of the healthy controls and from those with HBV/HIV coinfection." (PMID 30815625, 2019).
co-infection (continued). "LZD, vancomycin, or clindamycin significantly decreased pulmonary IL-6 and mKC levels at 4 h and the IFN-γ level at 24 h after MRSA co-infection, while the levels of IL-1β, TNF-α, and IL-12 were similar to those of the placebo group." (PMID 31849655, 2019). "Host-protein signature, CRP, IL-6, and PCT mean levels in mixed infections (bacterial and viral co-infection) are comparable to those found in pure bacterial infections (p > 0.14)." (PMID 29700762, 2018). "IL-6 was the only one to reach quantifiable levels for both HIV monoinfection and T. cruzi/HIV coinfection scenarios." (PMID 28824880, 2017). "Overall we could observe a tendency for reduced levels of IFN-γ, TNF, IL-6, and IL-10 in the serum of co-infected groups, when compared to P. yoelii 17XNL single infected group, suggesting a modulation of P. yoelii 17XNL induced immune response by Leishmania co-infection." (PMID 27446022, 2016). "We show that all three antibiotics decreased the maximal levels of pulmonary IL-6, mKC and IFN-γ, which play key roles in host immune response to coinfection." (PMID 23478252, 2013). "In the present study, we show that co-infection of human MDDCs with viable IAV and SP enhance the induction and secretion of IL-12p70, as well as IL-6." (PMID 23421931, 2013). "The co-infection with H3N2 SwIV and either SW114 or Nagasaki induced higher levels of IL-1β, TNF-α, IL-6, IL-12 and IL-10 compared to mock or H3N2 SwIV infection alone." (PMID 23157617, 2012). "However, we detected an elevation in MSP-119-specific IL-6 due to co-infection, so it is possible that the emergent IL-17/IL-23 axis described by Helmby may likewise be involved in our co-infection system, though not in organs that negatively impact short-term survival." (PMID 19951425, 2009). "The TAK-242/siRNA-treated IAV+SA group exhibited markedly decreased mRNA levels of inflammatory factors (NF-κB, IL-6, TNF-α) and adhesion molecules (ICAM-1, VCAM-1) compared with the uninfected IAV+SA group, confirming TLR4 as the key receptor mediating co-infection-induced inflammation." (PMID 40572089, 2025). "downregulates cytokines including IL-6, IL-22 and TGF-β and that co-infection with Plasmodium spp." (PMID 40148890, 2025). "An independent t-test was utilized to determine the comparison of serum IL-10 and IL-6 levels, while a Mann-Whitney test was used to establish the comparison of serum leptin levels in leprosy patients with and without helminth co-infection." (PMID 41239264, 2025). "To summarize, this study sought to assess whether co-infection of HNECs with both clinical and laboratory-grown isolates of PA and IAV would reduce PA biofilm biomass, increase PA virulence factors and alter IL-6 response in HNECs." (PMID 40788668, 2025). "This study aimed to measure the serum levels of IL-10, IL-6, and leptin in leprosy patients with and without helminth co-infections." (PMID 41239264, 2025). "Additionally, co-infection of pigs with NADC30-like PRRSV-2 strain SDlz1601 and S. suis upregulated IL-1β, IL-6, IL-8, TNF-α, CCL4, IL-10, and INF-β in PAMs." (PMID 38547254, 2024). "Thus, OKF6/TERT2 cells were infected with P. gingivalis, F. nucleatum, the co-culture of both bacteria, and the co-infection of both bacteria and then the mRNA levels of TNF-α, IL-1β, IL-6, and IL-8 were determined using RT-qPCR." (PMID 38612423, 2024). "Along these lines, our data from the co-infection experiments using S. aureus and H1N1 showed that in the presence of bacteria, at least some pro-inflammatory cytokines (i.e., IL-1β, IL-6, and TNF-α) and type II interferon IFN-γ are elevated on the protein level by H1N1 in M2-MDMs by tendency." (PMID 38261967, 2024). "Coinfection was not a significant predictor of fatality, but the lowest value of SpO2 registered and IL-6 levels were." (PMID 39768950, 2024).
co-infection (continued). "Furthermore, endonuclease therapies may prove safer than cytokine-blocking monotherapies, as they are unlikely to increase the risk of microbial co-infection associated with the neutralization of cytokines that are critical for immune defence such as IL-1β, IL-6 or GM-CSF." (PMID 39009040, 2024). "Clinically, late presentation was associated with coinfection rate; polysymptomatology; high IFN-ɣ, IL-6 and IL-10 levels; nonresponse to antiretroviral therapy; and virological failure- and tuberculosis coinfection-motivated changes to therapy." (PMID 38992229, 2024). "Additionally, some reports have described that the co-infection of both bacteria promotes increases in the expressions of TNF-α, IL-1β, and IL-6 in murine in vivo models." (PMID 38612423, 2024). "Further analysis discloses a higher level of IL-6 in patients with active double co-infection than in patients with latent infection/co-infection and without infection (p = 0.0319 and p = 0.0418, respectively)." (PMID 36653846, 2023). "Additionally, pro-inflammatory cytokines IL-1β, IL-6, CXCL2, and TNF-α are downregulated during co-infection compared to P. aeruginosa single-infection." (PMID 37305417, 2023). "In the present study, the levels of IL-2, IL-6 and TNF-α were markedly higher, while the level of IL-10 was markedly lower in HIV/HBV coinfection group than those in HBV infection group and control group, suggesting that HIV worsens HBV-induced inflammatory response." (PMID 38357144, 2023). "Moreover, patients have extreme elevations of HHV-8 viral load and IL-6 level; it has been reported that in HIV/HHV-8 coinfection, IL-4, IL-6, and IL-10 levels are increased." (PMID 35053573, 2022). "This may indicate that both IL-6 and IL-8 can indicate the lung bacterial infection of VSAA/SAA and the co infection of lung bacteria and fungi." (PMID 36319826, 2022). "To examine whether co-infection alters the induction patterns of cytokines and chemokines, we measured the serum levels of IP-10, MCP-1, TNF-α, IL-1-β, IL-6, IL-10, and IFN-γ over the course of infection using ELISA." (PMID 34711897, 2021). "So far, this protective action of IL-6 has not been described for co-infection scenarios with S. aureus." (PMID 34067487, 2021). "IL-6, an inflammatory cytokine, was significantly elevated at 7 and 10 dpi in the co-infection group, but not in the other groups." (PMID 34711897, 2021). "Expression of CCL2 remained elevated in lung of animals with co-infection while moderate, though non-significant, reductions of IL-1β and IL-6 were observed compared to the TB group." (PMID 32373548, 2020). "IL-6 secretion was not affected by F. nucleatum infection alone (23.1 ng/mL) or co-infection (21.39 ng/mL), but by P. gingivalis infection alone." (PMID 32244806, 2020). "Associations between the occurrence of ME/CFS clinical symptoms, HHV−6, HHV−7 and B19 infection/co-infection reactivation, and increased expression levels of TNF-α and IL6 have been observed, as well as alterations in the levels of infection markers of B19V and EBV." (PMID 32455633, 2020). "In order to further characterize the effects of IFN-γ and/or IL-6 neutralization on secondary pneumococcal infection following IAV infection, the established co-infection model was furthermore adjusted by reducing the infectious dose in the underlying IAV infection." (PMID 31474978, 2019). "IL-6 concentration in co-infection was not always higher than in single infection, but it increased as prolonged infection time." (PMID 32038632, 2019). "IL-6 is a commonly detected cytokine and one of the most induced immune markers during co-infection; however, its role in these infections has not been defined." (PMID 32038632, 2019). "However, in the co-infection mouse model employing the reduced viral dose, the neutralization of IFN-γ and IFN-γ together with IL-6 had clear effects on the concentrations of TNF-α, CCL-5, IL-1ß, and GM-CSF." (PMID 31474978, 2019).
co-infection (continued). "In a mouse model of vulvovaginal candidiasis (VVC), the fungal burden and the levels of pro-inflammatory cytokines, IL-1β, IL-6 and TNF-α showed a increase on co-infection with S. agalactiae, while the level of TH17 T cells and IL-17 in the cervicovaginal lavage fluid were significantly decreased." (PMID 29527193, 2018). "In order to further investigate why the majority of co-infections did not have an additive effect on the secretion of IL-6 and IL-8, we examined the signaling mechanisms of both pathogens." (PMID 29922270, 2018). "Co-infection of human bronchial epithelial cells (CFBE41o-) with both pathogens did not enhance IL-6 and IL-8 production beyond the levels observed following single infections." (PMID 29922270, 2018). "Despite the very low levels of IL-6 detected in the cats from this study, it is not possible to suggest that Th17 profile is depressed in favor of Tregs increase in retrovirus co-infection, due to the small number of FIV-positive cats." (PMID 30500849, 2018). "Finally, cytokines that increased during co-infection when compared to DENV mono-infection were IFN-ω (2.28 fold, p<0.001), TNF-α (1.94 fold, p<0.001) and IL-6 (1.64 fold, p = 0.003)." (PMID 28644900, 2017). "Those with Plasmodium mono-infection had higher levels of IL-4, IL-6, IL-10, IL-12, IL-13, IL-17A, IFN-γ, and MIP1-α/CCL3 compared with DENV mono-infection or co-infection; those with Plasmodium mono-infection had more cough than those with DENV mono-infection." (PMID 27128316, 2016). "Assessing the IL-6 inflammatory response in the supernatant of infected cells acts as a good indicator of whether or not co-infection will lead to an increased inflammatory response." (PMID 40788668, 2025). "Thus, in our study, modulation of the mRNA expression of the cytokines IL-1α, IL-6 and IFNα by H1N1pdm09 or SARS-CoV-2 may have promoted enhanced viral replication during co-infection." (PMID 39772252, 2024). "On mRNA level, compared to HRV infection alone (96 ± 127 fold change), co-infection with the non-mucoid PA isolate significantly increased IL-6 mRNA (4742 ± 8020 fold change, p = 0.04), whereas co-infection with the mucoid isolate did not (79 ± 108, p = 0.999)." (PMID 35265536, 2022). "IL-6 levels have been shown to be significantly elevated in the presence of a clinically relevant secondary bacterial infection, which may make its upregulation in pH1N1-MRSA coinfection unsurprising." (PMID 33202895, 2020). "Importantly, in this co-infection model, the neutralization of IFN-γ alone as well as the simultaneous neutralization of IFN-γ and IL-6 led to a significant reduction of the lung bacterial load in co-infected mice as compared to the control-treated co-infected mice." (PMID 31474978, 2019). "The hypothalamus appeared to be particularly responsive to lung co-infection, as we did not observe any difference in microglial or astrocyte morphology in the hippocampus and whilst TNFα expression was increased, IL-6, IL-1β and CCL-2 expression were unaltered." (PMID 29980196, 2018). "Interestingly, a clear synergistic effect on IL-6, CCL5 and TNF-α up-regulation could be observed after co-infection." (PMID 27213692, 2016). "Moreover, we found that IL-6 and TNF-α, generally induced by LPS, may promote BTLA expression on CD4+ T cells via the STAT3 and NF-κB signaling, which explains why HBV-ACLF patients with coinfection have elevated BTLA levels." (PMID 38418488, 2024). "While co-infection with the non-mucoid isolate and HRV16 led to almost complete degradation of endogenous and exogenous IL-6, co-infections with the mucoid isolate did not, which might, in part, be explained by altered expression, regulation or secretion of bacterial proteases." (PMID 35265536, 2022).